TNF (tumor necrosis factor)
Diseases named in the same sentence as TNF in open-access papers (continued):
Sharing a sentence is not in itself a finding about the gene and the disease.
psoriasis (continued). "This relationship was independent from changes in other metabolic/inflammatory parameters, in line with the absence of correlations between tumor necrosis factor and resistin changes observed in males with psoriasis who received retinoid treatment." (PMID 17479165, 2007). "TNF inhibitors are not FDA- approved for psoriasis, however, they are approved for other indications and physicians can prescribe them for psoriasis." (PMID 16756666, 2006). "Our results showed a significant attenuation of psoriasis symptoms (erythema, scaling, and skin thickness) in mice treated with intact hUCB-MSCs, hUCB-MSCs preconditioned with IL-22 and TNF-α, and hUCB-MSC-Exo preconditioned with IL-17, IL-22 and TNF-α (MSC-Exo 3C)." (PMID 40906403, 2025). "In addition to TNF-α inhibitors, biological treatments for psoriasis include anti-IL-17 agents such as secukinumab, and no increased incidence of major cardiovascular events has been reported with these treatments." (PMID 40584532, 2025). "Similarly, in the Th17-dominant setting of psoriasis, PRP regulates DC-T cell interactions by reducing peripheral blood Th17 cells, suppressing their secretion of IL-17, IL-22, and TNF-α, and enhancing the suppressive capacity of FOXP3+ Treg cells over effector T cells." (PMID 41246327, 2025). "Psoriasis-specific cytokines (e.g., IL-12, IL-17A, IL-23) did not promote chemokine expression, but TNF-α – which could indicate both infection and sterile inflammation – was able to induce CCL-2 and CXCL10 expression." (PMID 41264606, 2025). "A previous study showed that patients with OSA have higher levels of IL-6 and TNF-α, which are also found in patients with psoriasis and treatment of OSA patients who had refractory psoriasis with continuous positive airway pressure (CPAP) has been shown to reduce psoriasis severity." (PMID 40232659, 2025). "While secukinumab effectively managed the patient's ankylosing spondylitis after discontinuing anti-TNF therapy, its effect on psoriasis remains unclear, especially without initial IL-17 elevation." (PMID 40678000, 2025). "However, further data are urgently required due to unexpected findings in some studies where TNF inhibition for psoriasis does not reduce the rate of PsA development." (PMID 39150442, 2025). "Psoriasis, a multifactorial inflammatory condition, has prompted a growing interest in RNA-based therapies, particularly siRNA and miRNA approaches targeting STAT3, keratin 17, and TNF-α pathways, which aim to normalize keratinocyte behavior, suppress inflammation, and modulate angiogenesis." (PMID 40724842, 2025). "While highly effective in treating psoriasis, TNF-alpha inhibitors may not always resolve the type 1 interferon-driven component of psoriasis." (PMID 40546629, 2025). "The proportions of pro-inflammatory (TNF-α, IL-6, IL-17, IL-23, and IL-1β) and anti-inflammatory (IL-10) cytokines were assessed in the serum and cutaneous tissue of psoriatic animals produced by IMQ to assess the immunomodulatory impact of ERN in psoriasis-like inflammation." (PMID 40667480, 2025). "In psoriasis, these agents have been associated with significant reductions in Psoriasis Area and Severity Index (PASI) scores, independent of weight loss, by reducing cytokine expression (e.g., TNF-α) and potentially regulating immune cell activity, including peripheral regulatory T-cells." (PMID 39845205, 2024). "Here, we investigated the expression of psoriasis-related cytokines (TNF-α, IL-6, IL-22, IL-23, IL-17A, IL-17E, IL-17F, IL-4 and IL-10) in the inflamed skin after mannan exposure at the peak (day 4) and the end (day 7) of psoriasis with/without inhibitor(s) treatment." (PMID 38444844, 2024). "The active ingredients of the three tea alcoholic extracts could modulate multiple signaling pathways through a variety of target proteins such as TNF-α, IL-17, FLG, Cytokeratin 17, IL-23, STAT3, FLG, IFN-γ, IL-22, etc., and thus attenuate or inhibit psoriasis." (PMID 38542915, 2024).
psoriasis (continued). "TNFα is an important cytokine involved in the pathogenesis of several chronic immune-mediated inflammatory conditions, and therefore, blocking this signaling pathway was proven effective in the management of such diseases such as RA, PA, AS, IBD, JIA, and psoriasis." (PMID 39000125, 2024). "Interestingly, the course of psoriasis improvement remained consistent for patients using TNF-α inhibitors, irrespective of the season." (PMID 39519223, 2024). "Therefore, regardless of the treatment used, TNF-α levels were constantly significantly higher in the psoriasis group, making it possible to rebound at any time, especially when trying to end the treatment." (PMID 39044928, 2024). "None of the three paradoxical psoriasis to anti-TNF-α showed ADAMTSL5 positivity." (PMID 38495872, 2024). "Additionally, diminished serum adiponectin levels in psoriasis patients, along with a negative correlation with BMI, TNF-α, and IL-6 levels, suggest a potential anti-inflammatory role in inhibiting adipocyte adipogenesis and Th17 cell-mediated inflammation." (PMID 38550599, 2024). "Moreover, there was highly statistically significant variance in serum CRP and TNFα levels between responders and non-responders in psoriasis patients as regards PASI 50 (P < 0.0001)." (PMID 38965465, 2024). "Therefore, targeted intervention of IL16 signaling emitted by IS CD8+ T cells, as well as interfering with the reception of TNF signaling by IS CD8+ T cells, may be potential therapeutic targets for psoriasis." (PMID 38915827, 2024). "Additionally, IDG was shown to inhibit the expression of IL-6, IL-13, IL-17A, TNF-α, and MCP-1, suggesting that IDG may exert its therapeutic effects on psoriasis through its anti-inflammatory properties." (PMID 39465158, 2024). "In addition, ADAMTSL5 was not expressed in psoriasis reactions to anti-TNF-α, in line with previous findings showing an overactivation of innate immunity, and not adaptive responses, in these conditions." (PMID 38495872, 2024). "Nevertheless, it is found that statin improves psoriasis symptoms due to its immunomodulatory and anti-inflammatory effect through the inhibition of leukocyte function antigen-1 (LFA-1), interleukin-1 and -6, and tumor necrotic factor alpha (TNF-α), and its ability to reduce CRP levels." (PMID 39120229, 2024). "Moreover, there was highly statistically significant difference in serum CRP and TNFα levels between responders and non-responders in psoriasis patients as regards PASI 50 (P < 0.0001)." (PMID 38965465, 2024). "hs-CRP, IL-17A, and TNF-α in healthy controls, psoriasis patients with and without atherosclerosis." (PMID 39104857, 2024). "Psoriasis, autoimmune thyroiditis, Crohn’s disease, uveitis, and lichen sclerosus have shared pathogenesis involving the T helper 17 cells pathway, with increased levels of TNF-α, and anti-TNF-α therapy reducing T helper 17 cell differentiation and inflammatory cytokines." (PMID 38957840, 2024). "In addition, visfatin boosted the production of TNF-α-induced CXCL8, CXCL10, and CCL20 in human keratinocytes, as well as antimicrobial peptides such as CAMP, HBD-2, HBD-3, and S100A7 in a murine model of IMQ-induced psoriasis." (PMID 38929716, 2024). "Indeed, biologic drugs, such as anti-TNFα, IL17, and IL23, have been developed to specifically block the actions of these cytokines and reduce inflammation in psoriatic skin, revolutionizing the psoriasis treatment scenario." (PMID 37626687, 2023). "Given that RA and plaque psoriasis are both treated by many of the same TNF inhibitor therapeutics, there may be co-occurrence of RA with psoriasis, independent of the treatment." (PMID 37369753, 2023). "Interestingly, the incidence of Non-Melanoma Skin Cancer in psoriasis patients treated with TNF inhibitors is nearly six times higher compared to RA, underscoring the influence of disease-related factors, such as prior psoriasis phototherapy." (PMID 37795084, 2023).
psoriasis (continued). "In a model of imiquimod-induced psoriasis in mice, it was described an increase of Foxp3+ Tregs in the skin and restoration of their suppressive function following use of IL-17 or IL-23 blocking antibodies but not with an anti-TNF-α treatment." (PMID 36901778, 2023). "The results indicate that the effects of TNF-α or IL-17 inhibitors on UA or lipid metabolism may not always be parallel to those on skin rash in psoriasis." (PMID 36902720, 2023). "There is currently a lack of research on the expression of COX in psoriasis using TNF-α inhibitors." (PMID 38149053, 2023). "In contrast, methotrexate, a folate antagonist used for the treatment of severe inflammatory conditions, including psoriasis, did not reduce caspase-1 activity in psoriasis patients, suggesting that TNF-α inhibition is superior in reducing NLRP3-dependent inflammation during psoriasis." (PMID 37443800, 2023). "We stimulated sc and shP2 HPV-Kers with the combination of IL17A and TNFα, as it was previously established that the synergistic action of IL17A and TNFα on keratinocytes induces such transcriptomic changes that show a massive correlation with the psoriasis gene signature." (PMID 37351597, 2023). "Neutrophils secrete cytokines such as tumor necrosis factor alpha (TNF-α) and interleukin-8 (IL-8), and the chemotactic effect of these inflammatory factors leads to neutrophil infiltration in the psoriatic epidermis and promotes psoriasis inflammatory progression." (PMID 37160878, 2023). "In addition, the HA-ES group loaded with CUR showed relief of inflammatory symptoms according to the clinical psoriasis area and severity index (PASI), lower levels of TNF-α, IL-17A, IL-17F, IL-22, and IL-1β mRNA, and lower CCR6 protein expression compared to ES and PGS groups." (PMID 36678859, 2023). "In our patients with PsA, the most commonly prescribed DTT was anti-IL17 plus anti-TNF with a high efficacy rate (80% MCI) which suggests that this combination deserves more research as we have found only a case report on this DTT, which proved unsuccessful due to psoriasis activity." (PMID 37936691, 2023). "As such, many observational and non-controlled studies on TNF-a inhibitors have reported positive findings and suggest that these agents could lead to a reduction of cardiovascular events in patients with psoriasis." (PMID 36830855, 2023). "This study delineated that IκBζ may be a better target than TNFα or IL‐17A to manage psoriasis, as psoriasis‐like skin inflammation was still occurring in the absence of TNFα and IL‐17A, whereas it was completely missing in the absence of IκBζ." (PMID 36245291, 2022). "Thus, TNF-α blockade by TNF-α inhibitors may induce sustained IFN-α production, leading to the development of psoriasis." (PMID 35884790, 2022). "Increased oxidative stress and inflammatory mediators including tumor necrosis factor (TNF)-α, interferon gamma (IFN-γ), interleukin (IL)-1β, IL-6, IL-12, IL-17, IL-22 and IL-23, released by activated T-cells subsets, monocytes and dendritic cells, are involved in the pathophysiology of psoriasis." (PMID 35215285, 2022). "Functionally, this mechanism resulted in the infiltration of pro‐inflammatory cytokines such as TNF‐α, IL‐1β, IL‐6, IL‐17A, and CXCL‐15, which enhances the inflammatory response in skin lesions and reinforces the cross‐talk between neutrophils and keratinocytes, ultimately aggravating psoriasis." (PMID 35281792, 2022). "Anti-TNF treatment did not contribute to the psoriasis development in patients with IBD." (PMID 35801760, 2022). "Previous studies have shown that quercetin and luteolin could inhibit the activation of the NF-κB pathway, reduce the levels of serum inflammatory factors such as TNF-α, IL-6, and IL-17, and significantly reduce the PASI score of IMQ-induced psoriasis mouse models." (PMID 35265149, 2022).
psoriasis (continued). "In FFA4 KO mice, the levels of inflammatory TH23/TH17 axis cytokines (IL-17A, IL-22 and IL-23) and TH1 cytokines (IL-1β, IFN-γ and TNF-α) in the lymph nodes were also increased after psoriasis induction; however, Compound A treatment did not suppress the cytokine levels." (PMID 35562873, 2022). "However, in the current meta-analysis, post-anti TNF psoriasis in anti-TNF-treated IBD patients was not higher than that in anti-TNF-naïve counterparts." (PMID 35801760, 2022). "Thus, in this cohort of PsA patients with mild psoriasis, TNF blockade did not affect the protein levels of IL-17 cytokines and its receptors in skin and synovium, despite reduced cellular inflammation and improved clinical outcome for joint involvement." (PMID 35203534, 2022). "miR-146b facilitated miRNA-146a to inhibit the proliferation and psoriasis-related target gene expression (such as FERM domain containing kindlin 1 (FERMT1), NUMB endocytic adaptor protein (NUMB), etc.)in cultured human keratinocytes stimulated with IFN-γ or TNF-α." (PMID 35075118, 2022). "Briefly, in early-phase psoriasis, nucleic acids and a variety of antimicrobial peptides released from damaged keratinocytes activate innate immune cells, including plasmacytoid DC (pDC) and macrophages, which produce interferon (IFN)-α and tumor necrosis factor (TNF)-α." (PMID 35837394, 2022). "Several types of inflammatory skin diseases (such as psoriasis) are closely related to the activation of JAK/STAT signaling pathway, as the activation of this pathway can enhance the secretion of various pro-inflammatory cytokines (e.g., IL-17, IL-22, IL-23, and TNF-α)." (PMID 36618400, 2022). "This may explain IL-17, IL-23, and TNF-α whose biologics are effective for treating psoriasis but did not yield statistically significant results in our MR analysis." (PMID 35769988, 2022). "TNF-α blockade treatment significantly increased low-flow-mediated constriction (l-FMC), but not FMD, suggesting that such anti-inflammatory treatment improves vascular function in psoriasis patients, mainly by altering the baseline vascular tone, but not the vascular reactivity to given stimuli." (PMID 35883760, 2022). "Based on our study, anti-TNF agents may be used for IBD treatment without concern for psoriasis development." (PMID 35801760, 2022). "Biologics targeting TNF-α can induce a wide range of immunological responses ranging from IFN-y dominant responses such as vitiligo and alopecia areata (Th1), Th17-mediated skin disorders such as psoriasis and palmoplantar pustulosis but also Th2-induced disorders such as eczema." (PMID 33802483, 2021). "In addition, compared with the IMQ group, the protein expression of IL-17a (p = 0.008) and TNF-α (p = 0.016) in the back lesions decreased in the IMQ + TDG group on day 12, which are inflammatory factors involved in the pathogenesis of psoriasis." (PMID 33995034, 2021). "However, TNF-α inhibitors are a good choice for patients diagnosed with moderate to severe psoriasis and psoriatic arthritis who are no longer suitable for conventional treatment." (PMID 34201974, 2021). "The aim of the study was to investigate the influence of 36-month therapy with TNF-α inhibitors (adalimumab, etanercept, infliximab) on the levels of adipokines (resistin, adiponectin, leptin) and lipids (TG, cholesterol, LDL, HDL) in 37 psoriasis patients and 30 healthy controls." (PMID 33927259, 2021). "Moreover, the expression levels of other cytokines, including IL-17F, IL-23, IFN-γ, and TNF-α, were of no corresponding relationship with the states of mouse psoriasis-like phenotype." (PMID 34881280, 2021). "Moreover, some plants, including Datura Metel L. mustard seed and rosmarinic acid (RA), play a protective role against the development of imiquimod-induced psoriasis by inhibiting NLRP3 inflammasome activation by cytokines, such as IL-1β, IL-6, IL-8, CCL20, and TNF suppression." (PMID 34072753, 2021).
psoriasis (continued). "Furthermore, the levels of inflammatory cytokines, including IFN-γ and TNF-α, do not differ between peripheral blood NK cells from psoriasis patients and healthy controls." (PMID 32917058, 2020). "Providers should engage in shared decision-making to determine whether patients on tumor necrosis factor-alpha inhibitors for psoriasis should receive the MMR vaccine without an interruption in biologic therapy." (PMID 32258339, 2020). "However, administration of IFN-γ and TNF-α does not reproduce psoriasis pathology, suggesting that Th1 cell induction of experimental psoriasis cannot be fully explained by Th1 cytokine function." (PMID 32917058, 2020). "Previous studies demonstrated that the pro-inflammatory cytokines, including TNF-α, IL-6, IL-1β, IL-17A, and IL-22 were up-regulated in psoriatic skin tissues and serum, and the IL-23/IL-17 axis was found to participate in the regulation of IMQ-induced psoriasis-like skin inflammation." (PMID 32515468, 2020). "However, keratinocyte proliferation is not directly induced by IFN-γ or TNF-α, and the pathogenesis of psoriasis is not fully explained by Th1 hyper-activation alone." (PMID 33171607, 2020). "The results determined that psoriatic keratinocyte exosomes could significantly promote the formation of NETs and subsequent expressions of IL-6, IL-8, and tumor necrosis factor-alpha (TNF-α) in neutrophils, which have been reported to play a critical role in psoriasis." (PMID 32993791, 2020). "A retrospective cohort study done on patients' diagnosis with either of RA or psoriasis treated with TNFα inhibitors, methotrexate, HCQ, and other nonbiologic DMARDs reported the reduced relative risk of DM for TNFα inhibitor and HCQ compared with other nonbiologic DMARDs." (PMID 32190699, 2020). "Psoriasis is marked by the Th-1 and Th-17 polarization of the adaptive immune response, later followed by the increase in expression of inflammatory mediators like interferon gamma (IFN-γ), tumor necrosis factor alpha (TNF α), interleukin-2 (IL-2), and interleukin-17 (IL-17)." (PMID 33262910, 2020). "On the contrary, the dDCs that infiltrate the epidermis during active psoriasis are absent in resolved epidermis after UVB or during anti‐TNF treatment, indicating a more strict correlation between the presence of infiltrating DCs (iDCs) in epidermis and the clinical disease." (PMID 32757303, 2020). "TNF-α concentration (↑69.77%, p ≤ 0.0001; ↑103.32%, p ≤ 0.0001, respectively) and IL-2 (↑45.10%, p ≤ 0.0001; ↑67.65%, p ≤ 0.0001, respectively) in SWS of patients with psoriasis with normal and decreased saliva secretion was significantly higher than in the control group." (PMID 32164227, 2020). "In addition, TNF-α and IL-6 expression were downregulated in unstimulated peritoneal macrophages from CX3CR1−/− mice, consistent with our previous report on imiquimod-induced psoriasis-like skin inflammation model in CX3CR1−/− mice." (PMID 33036460, 2020). "Although this is the first trial of narrowband UVB phototherapy for CIS, in people with psoriasis for whom this treatment has been a mainstay, UVB exposure decreases the levels in skin of inflammatory cytokines such as TNF-α, IFN-γ, and IL-17, that may influence B cell maturation." (PMID 31138860, 2019). "As there are other slan-negative antigen presenting cells producing IL-23 and TNF-α in psoriasis skin lesions, it remains to be elucidated whether slanMo have a unique and non-redundant stimulatory role in psoriasis skin inflammation." (PMID 31191513, 2019). "In addition, studies has suggested that cytokines including type 1 IFNs, TNF, and IL17, are interwoven, and each of these cytokines is the cornerstones of an inflammatory triangle that drives the development and maintenance of psoriasis." (PMID 31293591, 2019). "However, as we have learned from TNF-α antagonists in psoriasis, this finding does not exclude their efficacy." (PMID 31440261, 2019).